SCN1A (sodium voltage-gated channel alpha subunit 1)
Diseases named in the same sentence as SCN1A in open-access papers (continued):
Sharing a sentence is not in itself a finding about the gene and the disease.
myoclonic seizures (8 papers, 2012 to 2024). "In those with seizure onset before age of 1 year, fever sensitivity, and history of myoclonic seizures, testing for SCN1A variants might be undertaken directly." (PMID 34268891, 2021).
Acute encephalopathy (6 papers, 2014 to 2023). "Recently, a mutation of the SCN1A gene (codes neuronal sodium channel alpha 1 subunit) was found to be the predisposing factor for the onset of various types of acute encephalopathy." (PMID 23755112, 2014). "Vaccination, particularly for pertussis, may also trigger acute encephalopathy in children having a SCN1A mutation." (PMID 36761411, 2023).
Brugada syndrome (6 papers, 2017 to 2025). A genetically heterogeneous condition characterized by complete or incomplete right bundle branch block accompanied by ST elevation in leads V1-V3. "The non-affected mother (I:2) had family history of Brugada syndrome and showed the variants in KCNQ2 and SCN1A genes." (PMID 29261713, 2017).
myoclonic epilepsy of infancy (6 papers, 2009 to 2023). Myoclonic epilepsy of infancy is a rare self-limited epileptic syndrome characterized by brief myoclonic seizures in previously healthy and developmentally normal children in the first three years of life. "Mutations in the voltage-gated sodium channel subunit gene SCN1A are identified predominantly in patients with DS, also known as severe myoclonic epilepsy of infancy (SMEI), and in the families with GEFS+." (PMID 35002916, 2021).
neuroblastoma (6 papers, 2016 to 2024). Neuroblastoma (NB) is the most common solid, extracranial childhood tumor. "The lung cancer cells H460 only express SCN3A and SCN9A, whereas the neuroblastoma cells SHSY express SCN1A, SCN2A, SCN3A, and SCN9A." (PMID 31329011, 2019).
Angelman syndrome (5 papers, 2019 to 2025). A neurogenetic disorder characterized by severe intellectual deficit and distinct facial dysmorphic features. "Clinical syndromic diagnoses were established prior to genetic testing for 5/70 (7.1%) individuals in the non-SCN1A cohort: two individuals with Angelman syndrome, and one individual each with Lennox–Gastaut syndrome, Landau–Kleffner syndrome and Jeavons syndrome." (PMID 39882024, 2025).
Dystonia (5 papers, 2019 to 2025). An abnormally increased muscular tone that causes fixed abnormal postures. "It is already known that single gene disorders, including SCN1A, SCN2A, KCNQ2, PRRT2, and pyridoxine deficiency, can result in isolated dystonia; we add CdLS5 (HDAC8 variation) to this expanding spectrum." (PMID 38910710, 2024). "Since it is already known that single gene disorders, including SCN1A, SCN2A, KCNQ2, PRRT2, and pyridoxine deficiency, can result in isolated dystonia, we add CdLS5 (HDAC8 variation) to this expanding spectrum." (PMID 38910710, 2024). "In SCN1A‐linked early infantile DEE, seizures and epileptic spasms are observed beginning at an average of 9 weeks of age, with concomitant development of hyperkinetic movement disorders, including choreoathetosis, dystonia, myoclonus, and perioral hyperkinesia." (PMID 31709768, 2019).
sleep disorder (5 papers, 2013 to 2025). A change from the patient's baseline sleeping pattern, in the hours slept and/or an alteration/dysfunction in the stages of sleep. "Indeed, results show that sleep disorder in Scn1a+/- mice arises from loss of NaV1.1 channels in forebrain GABAergic interneurons." (PMID 41151066, 2025). "This gene is homologous with human genes SCN1A, SCN2A and SCN3A, which encode sodium channels and have been associated with neuronal and sleep disorders." (PMID 35189951, 2022).
Epileptic spasm (4 papers, 2017 to 2022). A sudden flexion, extension, or mixed extension-flexion of predominantly proximal and truncal muscles that is usually more sustained than a myoclonic movement but not as sustained as a tonic seizure. "In this series, 8/36 patients (22.2%) had epileptic spasms, including those with KCNT1, SCN2A, SCN1A, DOCK6 and PCDH19 variants." (PMID 35715422, 2022).
infantile epileptic encephalopathy (4 papers, 2017 to 2023). an epileptic condition characterized by epileptiform abnormalities associated with progressive cerebral dysfunction. "DS is a severe infantile epileptic encephalopathy, caused by de novo mutations in SCN1A, encoding the α-1 subunit of the voltage-gated sodium channel NaV1.1." (PMID 37419110, 2023).
Sudden unexpected death in epilepsy (4 papers, 2021 to 2025). "This method, referred to as Targeted Augmentation of Nuclear Gene Output (TANGO), resulted in restoration of SCN1A expression in a Dravet mouse model with a reduction of seizures and Sudden Unexpected Death in Epilepsy (SUDEP)." (PMID 33411776, 2021). "SCN1A variants are associated with Autism Spectrum Disorder (ASD), Sudden Unexpected Death in Epilepsy (SUDEP) and other neurological manifestations." (PMID 40903466, 2025).
Focal cortical dysplasia (3 papers, 2022 to 2025). A type of malformation of cortical development that primarily affects areas of neocortex. "Additionally, cluster #2, which focuses on focal cortical dysplasia (FCD), also shows a high incidence, as not only mutations in SCN1A and SCN2A that lead to excessive neuronal excitation result in FCD, but mutations in genes encoding potassium channels can also produce similar outcomes." (PMID 40667464, 2025).
Genetic Epilepsy Febrile Seizures plus (3 papers, 2013 to 2021). "Phenotypes caused by de novo SCN1A pathogenic variants are very variable, ranging from the severely affected patients with DS to much milder cases of genetic epilepsy febrile seizures plus (GEFS+)." (PMID 35002916, 2021).
glioblastoma (3 papers, 2015 to 2025). The most malignant astrocytic tumor (WHO grade IV). "In the CNPI, this means editing genes such as SCN1A, DEPDC5, or KCNQ2 in focal epilepsy, or IDH1, TERT, or PTEN in glioblastoma, while also ensuring specificity and limiting collateral damage to the patient." (PMID 40806492, 2025).
Huntington disease (3 papers, 2022 to 2023). Huntington disease (HD) is a rare neurodegenerative disorder of the central nervous system characterized by unwanted choreatic movements, behavioral and psychiatric disturbances and dementia. "The RACK1 gene can modulate neurodegeneration by promoting ERK degradation in Machado-Joseph disease (MJD) and Huntington’s disease (HD) models and participates in the process of neuronal differentiation by regulating SCN1A expression." (PMID 36161179, 2022).
memory impairment (3 papers, 2017 to 2025). "In summary, Scn1a ± mice exhibited increased levels of eEF2 phosphorylation that were associated with EEG alterations and a greater responsiveness to seizures accompanied by behavioral abnormalities including memory impairment, ASD like behavior and motor coordination problems." (PMID 34980259, 2022). "This was supported by studies investigating Scn1a mutant mice and in HCN1 (R43Q) mutants where prior induction of seizures before cognitive testing led to significant memory impairments." (PMID 41585885, 2025).
Nystagmus (3 papers, 2017 to 2024). Rhythmic, involuntary oscillations of one or both eyes related to abnormality in fixation, conjugate gaze, or vestibular mechanisms. "Seizures and ophthalmological abnormalities (nystagmus—visual impairment) are hallmarks of the SCN1A phenotype." (PMID 39568674, 2024).
Parkinson’s (3 papers, 2023 to 2024). "The authors decided that the origin of parkinsonism in DS remained uncertain, with unclear links to severe SCN1A gene mutations or persistent seizures treated with various high-dose AEDs." (PMID 39459422, 2024).
Down syndrome (2 papers, 2018 to 2024). "None of the enriched sets of pathways and functions associated with SCN1A was associated with the Down syndrome genes (DYRK1A, PSMG1, RCAN1, DSCR3, DSCR4) or with TSC2." (PMID 29518120, 2018).
episodic ataxia (2 papers, 2009 to 2023). "With our report, three major neuronal voltage-gated sodium channel genes (SCN1A, SCN2A, and SCN8A) have now been implicated as causative genes of episodic ataxia." (PMID 38251463, 2023).
infantile epilepsy (2 papers, 2013 to 2022). "Moreover, the most prevalent genetic diagnoses for infantile epilepsy, particularly for patients aged < 12 months, were KCNQ2, PRRT2, and SCN1A." (PMID 35720076, 2022).
Landau-Kleffner syndrome (2 papers, 2020 to 2022). A rare form of epileptic encephalopathy with spike-wave activation in sleep (EE-SWAS) characterized by various combinations of acquired cognitive, language, behavioral, and motor deficits associated with marked spike- and- wave activation in sleep. "Patients with SCN1A (p.R604H, p.T1250M and p.T1174S) variants were reported to have Rolandic epilepsy." (PMID 35663268, 2022).
lung carcinoma (2 papers, 2019 to 2023). "So far, there have been no reports on other three down regulated mRNAs (KCND3, SCN1A and CYB561D1) in lung cancer targeted by miRNAs." (PMID 37185598, 2023).
sudden infant death syndrome (2 papers, 2009 to 2022). Unexpected death in infancy which remains unexplained following autopsy, review of the medical history, and investigation of the death circumstances and death scene. "SCN1A has been associated with an increased risk of childhood seizures and sudden infant death syndrome." (PMID 35102242, 2022).
temporal lobe epilepsy (2 papers, 2016 to 2024). A localization-related (focal) form of epilepsy characterized by recurrent seizures that arise from foci within the temporal lobe, most commonly from its mesial aspect. "The drug-resistant temporal lobe epilepsy (TLE) has recently been associated with single nucleotide variants (SNVs) in microRNA(miR)-146a (MIR-146A) (rs2910164) and Sodium Voltage-Gated Channel Alpha Subunit 1 (SCN1A) (rs2298771 and rs3812718) genes." (PMID 38892194, 2024).
transient ischemic attack (2 papers, 2018 to 2024). A brief attack (from a few minutes to an hour) of cerebral dysfunction of vascular origin, with no persistent neurological deficit. "Her symptoms were first suspicious of a transient ischemic attack (TIA), but they were eventually diagnosed as FHM with a c.4495T>C mutation being found in the SCN1A gene." (PMID 30498473, 2018).
African trypanosomiasis (1 paper, 2024). "SCN1A was involved in African trypanosomiasis, AGE-RAGE signaling pathway in diabetic complications, and complement and coagulation cascades." (PMID 38846945, 2024).
Alkalosis (1 paper, 2025). Depletion of acid or accumulation base in the body fluids. "However, despite their normal appearance, previous work suggests 2-week-old Scn1a+/– mice are prone to febrile seizures, a hallmark feature of DS potentially triggered by heat-induced respiratory alkalosis." (PMID 40924494, 2025).
Bradycardia (1 paper, 2013). A slower than normal heart rate (in adults, slower than 60 beats per minute). "Administration of PTZ led to marked bradycardia, which may be similar to previously observed seizure-induced bradycardia and similar to that observed in Scn1a+/- mice following acute hyperthermia induced seizures." (PMID 24155976, 2013).
breast carcinoma (1 paper, 2024). "Alternatively, despite the lack of evidence of any apparent correlation with cancerous EMT, IQSEC3 was identified as a novel prognostic marker for breast cancer patients, and it is known that SCN1A is a possible factor in the development of chemoresistance in esophageal adenocarcinoma." (PMID 38790973, 2024).
diphtheria (1 paper, 2024). A Gram-positive bacterial infection caused by Corynebacterium diphtheriae. "Further supportive of variable expressivity, SCN1A:c.2176+2T>A affecting the exact same nucleotide was recorded in a patient with onset of afebrile seizure at age 5.1 months after Diphtheria-Tetanus-Pertussis (DTP) vaccination." (PMID 38891831, 2024).
Duchenne muscular dystrophy (1 paper, 2024). Duchenne muscular dystrophy (DMD) is a neuromuscular disease characterized by rapidly progressive muscle weakness and wasting due to degeneration of skeletal, smooth and cardiac muscle. "Similar observations have been made in previous ASO screens for exon skipping therapies, such as DMD for Duchenne muscular dystrophy and SCN1A for Dravet syndrome." (PMID 38714659, 2024).
Generalized myoclonic seizure (1 paper, 2024). A generalized myoclonic seizure is a type of generalized motor seizure characterized by bilateral, sudden, brief (<100 ms) involuntary single or multiple contraction of muscles or muscle groups of variable topography (axial, proximal limb, distal). "Previous reports of synonymous variants with a pathogenic impact include the SCN1A:c.693A>T:p.P231P variant detected in a patient with generalized myoclonic seizures." (PMID 38891831, 2024).
hepatoblastoma (1 paper, 2016). Hepatoblastoma (HB) is a malignant hepatic tumor and is the most common pediatric liver cancer. "Cytogenetic data of hepatoblastoma have revealed that up-regulation of GALNT5, DAPL1, ERMN, SCN1A and SCN3A plays a major role in the development and progression of the disease." (PMID 27322213, 2016). "However, the post-translational modifications regulated by GalNAcT5 in hepatoblastoma cells remain undefined, as the mechanism of action of DAPL1, ERMN, GALNT5, SCN1A and SCN3A genes." (PMID 27322213, 2016).
Hypertension (1 paper, 2024). The presence of chronic increased pressure in the systemic arterial system. "With regard to genes encoding Na+ channels, Scn9a was persistently upregulated in the RVLM with the exception of 12 wk, whereas Scn8a and Scn1a appeared to show upregulation in the NTS around the onset of hypertension at 10 and 12 wk." (PMID 38145287, 2024).
intracranial hemorrhage (1 paper, 2024). Bleeding within the SKULL, including hemorrhages in the brain and the three membranes of MENINGES. "Other causes include intracranial hemorrhage and genetic or metabolic disorders such as SCN1A mutations." (PMID 39803052, 2024).
malnutrition (1 paper, 2023). Inadequate nutrition resulting from poor diet, malabsorption, or abnormal nutrient distribution. "However, we hypothesized these rat models may be better suited to evaluate the pathogenic alterations directly caused by Scn1a defects, while minimizing the influences of spontaneous seizures and malnutrition." (PMID 36998780, 2023).
microcephaly (1 paper, 2023). A congenital or acquired developmental disorder in which the circumference of the head is smaller than normal for the person's age and sex. "In a young boy experiencing fever-induced focal seizures since the age of 7 years, along with microcephaly and mild dysmorphic signs, we detected a novel variant in the SCN1A gene [c.5379del, p.(Glu1794Lysfs7)], Clinvar ID 1375417." (PMID 38328757, 2023).
Myoclonic absence seizure (1 paper, 2021). "The second case was a 2‐year‐old White boy with refractory myoclonic absence seizures and a de novo pathogenic variant in SCN1A (p.Arg101Gln)." (PMID 34816733, 2021).
Neurodevelopmental delay (1 paper, 2022). "The patient from family 2, carrier of a de novo variant in the SCN1A gene, NM_001165963: c.3971 T > C, p.L1324P, presented neurodevelopmental delay and early-onset seizures." (PMID 36207321, 2022).
orchitis (1 paper, 2025). Inflammation of one or both testes due to viral or bacterial infections. "Thirdly, it has been shown that the severity of orchitis in Scn1a knockout mice is greatly influenced by the genetic background of the strain." (PMID 40003892, 2025).
sialorrhea (1 paper, 2023). "Following heat exposure, Scn1a+/RX mice showed cortical spikes and sialorrhea (drooling) as the body core temperature approached 40°C." (PMID 37551713, 2023).
sudden cardiac death (1 paper, 2017). "Among these genetic anomalies, only four variants, i.e., KCNQ1, KCNE1, SCN1A, and CACNA1C, were previously associated with SUDEP or other disorders associated with sudden cardiac death (SCD)." (PMID 29261713, 2017).
Thrombocytopenia (1 paper, 2024). A reduction in the number of circulating thrombocytes. "Based on the indirect interaction between MYH9 and SCN1A, common pathways, and co-expression, a digenic model was built to explain recurrent seizures and thrombocytopenia in the patient." (PMID 39202364, 2024). "The thrombocytopenia of the patient can only be explained by the variant of MYH9, which means the variant in SCN1A accounts for the seizure phenotype, and the variant in MYH9 leads to thrombocytopenia in the bone marrow of the patient independently." (PMID 39202364, 2024). "Here, we report a child with pathogenic missense variants in SCN1A and MYH9 simultaneously, presenting with phenotypes of recurrent seizures and thrombocytopenia." (PMID 39202364, 2024). "Further analysis showed that MYH9 might be a modifier of SCN1A, and the variant in MYH9 might not only influence the severity of SCN1A-related seizure but also lead to thrombocytopenia in the bone marrow." (PMID 39202364, 2024). "Meanwhile, for the phenotype of thrombocytopenia, we found that in the bone marrow, the expression of SCN1A is very low, indicating that SCN1A might have little effect on the patient’s hematological system phenotypes." (PMID 39202364, 2024). "In conclusion, from our digenic network, we proposed that in the cerebral cortex, the variant of MYH9 might work as a modifier of SCN1A and, in this family, led to intra-family seizure phenotype variability, whereas in the bone marrow, the variant of MYH9 has probably led to thrombocytopenia." (PMID 39202364, 2024). "In the cerebral cortex, the seizure phenotype of SCN1A may be modified by MYH9, whereas in the bone marrow, MYH9 may have an independent dual molecular effect, leading to thrombocytopenia." (PMID 39202364, 2024).
thyroid carcinoma (1 paper, 2021). "For instance, we failed to explore the role of the 5 feature genes (BMP8A, ADARB2, SALL3, PPBP, and SCN1A) in onset and progression of thyroid carcinoma by molecular experiments, cell experiments, or animal experiments." (PMID 34697553, 2021).
neurodevelopmental disorder (20 papers, 2016 to 2025). A behavioral and cognitive disorder with onset during the developmental period that involves impaired or aberrant development of intellectual, motor, or social functions. "The purpose of this study was to demonstrate the performance of a fully automated, deep learning-based brain segmentation (DLS) method in healthy controls and in patients with neurodevelopmental disorders, SCN1A mutation, under eleven." (PMID 38383725, 2024). "The CNVs involved known disease genes (EHMT1, MBD5 and SCN1A) and imbalances in genomic regions associated with neurodevelopmental disorders (16p11.2, 16p13.11 and 2q13)." (PMID 27113213, 2016). "Furthermore, other neurological and neurodevelopmental disorders, such as hemiplegic migraine and autism spectrum disorders, have now been described in the context of SCN1A variants." (PMID 34925043, 2021). "A recent article has identified high frequency of de novo mutations or variants (DNMs) in few genes which include PURA, SATB2, SCN1A, and TUBA1A and these are mostly found in cases of neurodevelopmental disorders (NDDs)." (PMID 39263390, 2024). "Given that alteration in Akt pathway is known to be involved in the pathogenesis of neurodevelopmental disorders, our data might suggest that the restored level of phosphorylated Akt might contribute to the rescue of the behavioral alterations observed in the Scn1a ± mice after eEF2K deletion." (PMID 34980259, 2022).